CCNE1 (cyclin E1)
Diseases named in the same sentence as CCNE1 in open-access papers (continued):
Sharing a sentence is not in itself a finding about the gene and the disease.
tumor (continued). "With these cells, we set up a transwell migration assay whereby activated CD8+ T cells were seeded in the top chamber, on top of a monolayer of either glyCAF or non-glyCAF and allowed to migrate towards a gradient of CXCL10 and Ccne1+ tumor cells in the bottom chamber." (PMID 38509063, 2024). "It was revealed that the growth of xenograft tumors developed from shAURKB-transfected cells was substantially inhibited compared with the control group; however, the introduction of CCNE1 overexpression readily abrogated the inhibition of AURKB knockdown on tumor growth." (PMID 38713155, 2024). "CCNE1 amplification rates were significantly lower in BRCA1/2 mutated tumours compared to BRCA-wildtype, although the difference did not remain significant after multiple testing corrections." (PMID 37474499, 2023). "A composite biomarker signature incorporating low Rb score (defined as <1% tumor cells with positive nuclear staining on immunohistochemistry), high cyclin E1 (defined as ≥10% tumor cells with positive nuclear staining on immunohistochemistry), and ESR1 mutation was associated with poorer PFS." (PMID 37035239, 2023). "Moreover, we further analyzed the correlation between CCNE1 expression and tumor purity, B cell, CD8 + cell, CD4 + cell, macrophage, neutrophil and dendritic cell (DC) in UCSC, LUSC, SARC and STAD via the TIMER portal." (PMID 36964635, 2023). "However, the deletion of Ccne1 in HSCs resulted in a significant reduction of absolute tumor numbers and the cumulative tumor size." (PMID 37620309, 2023). "According to TMB, MSI, neoantigen, and ICP analyses, CCNE1 may be a potential therapeutic target, particularly for immunotherapy, for a variety of tumor types." (PMID 36964635, 2023). "The relationships between CCNE1 expression and tumor grade were analyzed via the GEPIA2 portal." (PMID 36964635, 2023). "In neoplasia, CCNE1 protein overexpression is uncoupled from the cell cycle." (PMID 36572991, 2023). "Our results reveal novel functions for JUNB in cell proliferation and tumor aggressiveness through regulation of cyclin E1 and TGF-β2 expression, which might be exploited for cancer prognosis and therapy." (PMID 36494864, 2022). "Expression levels of seven CBX7 targets, namely Wnt10a, Ccne1, Fgfr2, Bhlhe22, Klhdc8a, Pde10a, and Dusp4, which had been significantly inhibited in miR-181ab1 KO compared to WT tumours in mice, were also significantly lower in either iClust2 or iClust3 than iClust1 HCCs." (PMID 35867177, 2022). "In addition, as a potential tumor suppressor gene, C2orf40 inhibits the expression levels of cell cycle-related proteins (CCNE1 and CDK1), and blocks the cell cycle in G2/M phase." (PMID 35676661, 2022). "Cyclin E1 is an established oncogene that is genomically amplified in numerous cancer types, and its overexpression corresponds with cell cycle mis-regulation, genome instability, cellular transformation, and tumor formation in mice." (PMID 36496990, 2022). "Similarly, the protein expression of Cyclin E1 has also been reported to be higher in RCC and associated with RCC tumor behavior." (PMID 34975298, 2022). "Importantly, tumor-specific alterations such as ATM loss and Cyclin E1 (CCNE1) amplification are more sensitive to ATR inhibition and are being exploited in synthetic lethality (SL) strategy." (PMID 35458687, 2022). "Furthermore, tumours with high-level amplifications in CCNE1 and MYC exhibited expected distributions of gene amplifications within signature assignments and cis-acting gene expression correlates." (PMID 36517593, 2022). "Altogether, our analysis suggests that the consistent downregulation of TTLL11 across tumors may be explained by the overexpression of CCNE1 or CDC25A as part of a tumor-specific transcriptional program." (PMID 36414642, 2022).
tumor (continued). "Signature RS1 (47%) was associated with ecDNA events encompassing (log odds 3.28, p-value = 0.004, logistic regression) and increased expression of CCNE1 compared to other tumours (log odds 0.88, p-value = 1.55 × 10−4, logistic regression, p = 7.5 × 10-7, Wilcoxon rank sum test)." (PMID 35396535, 2022). "In accordance with this study findings, high CDCA5 expression may contribute to tumor proliferation via regulating cyclin E1 expression." (PMID 36428736, 2022). "CBX7-mediated tumour suppression is in part through inhibition of of cyclin E1." (PMID 35867177, 2022). "Based on existing pre-clinical data showing that CCNE1 amplification is present in HGSC precursor lesions, we hypothesize that CCNE1 amplification will be a truncal event found across all sites of disease when amplified in the primary tumor." (PMID 34485660, 2021). "Furthermore, in vivo interference of CCNE1 effectively inhibited tumor cell proliferation in a xenograft mouse model." (PMID 34070839, 2021). "CCNE1 copy number of non-tumor internal controls across all samples were diploid." (PMID 34485660, 2021). "As CDK2 expression was aberrant in poorly differentiated G3 tumours, it can be speculated that the CCNE1-driven HCC progression may depend on CDK2-expression levels at a late stage." (PMID 34830835, 2021). "Studies have shown that microRNA such as miR-204, miR-375, and miR-3178 could play important roles in the occurrence and development of TNBC, while microRNA could also participate in the regulation of CCNE1 in tumor." (PMID 33791304, 2021). "If validated, these findings could lead to better selection of patients for antiangiogenic therapy and improved identification of CCNE1-overexpressing OCs as a different class of tumours that merit a particular treatment approach." (PMID 34567247, 2021). "To determine whether the interference of CCNE1 shows a suppressive effect on tumor growth, we conducted an in vivo assay using a xenograft mouse model." (PMID 34070839, 2021). "All investigated tumour tissues displayed enhanced Ccne1 gene expression." (PMID 34830835, 2021). "Interestingly, Ccne1-depleted tumours also displayed reduced levels of Ccnd1 and Ccna2 compared to WT mice." (PMID 34830835, 2021). "Thus, cyclin E1/CDK2 activation coupled with tumor suppressor FBW7 loss can promote CIN and tumor progression through reducing CENP-A’s centromeric localization, leading to centromere dysfunction." (PMID 32708729, 2020). "However, the precise mechanism driving NF90 to regulate RNA processing, such as tumor related mRNA cyclin E1 or VEGF, in tumor progression is still poorly understood." (PMID 32123579, 2020). "Similarly, in epithelial ovarian cancer, miR-424-5p also played a tumor-suppressing role by inhibiting CCNE1 expression and obstructing cell cycle in G1/G0 phase." (PMID 32065781, 2020). "In this study, we assessed whether oncogene-induced replication stress as a result of Cyclin E1 or Cdc25A overexpression affects mitotic behavior of tumor cells and genome instability." (PMID 33028815, 2020). "The results indicate that NT1721 might, at least partially, decrease the cell cycle progression and thus tumor growth through CCNE1 and CDK2 downregulation." (PMID 31661013, 2019). "In addition, we predicted and verified that the effect of TSG101 on the growth of tumor was related to elevated c-myc protein levels, accompanied by up-regulated cyclin E1/cyclin-dependent kinase 2 (CDK2) complex." (PMID 30675171, 2019). "AZD5438 had superior anti-tumor activity in models with higher copy number of CCNE1." (PMID 29433585, 2018). "Interestingly, one case with AAV2 insertion (FR2141T) also displayed an amplification of CCNE1 locus including the viral sequence, suggesting a two-step selection of CCNE1 activation in the natural history of this tumor." (PMID 30531861, 2018).
tumor (continued). "In the present study, the CDK1/2/9 inhibitor AZD5438 exerted significant tumor inhibition in two PDX models with high copy number of CCNE1, and we also found that AZD5438 exerted antitumor activity by inhibiting the expression of CDK2, CCNE1, and phosphorylated retinoblastoma (pRb)." (PMID 29433585, 2018). "The analysis of chemoresistant patients showed that the acquired resistance to chemotherapy was associated with inactivating gene breakages at the level of the tumor suppressors RB1, NF1, RAD51B and PTEN and resistant/refractory tumors are frequently associated with CCNE1 amplifications." (PMID 29389895, 2018). "We therefore aimed to test the hypothesis that platinum-based chemotherapy has greater cytotoxic effect on non CCNE1-amplified tumor cells, thus resulting in enrichment for CCNE1-amplified cell population, which might underlie and boost disease recurrence." (PMID 28977941, 2017). "Many of these genes, including those encoding bFGF, MAPK10, MAP3K5, IL1R2, E-cadherin, Ki67, Cyclin E1, beta-catenin, 14-3-3 protein T-cell (YWHAQ), integrin alpha-V (ITGAV), integrin alpha-10 (ITGA10), CDK6, PCNA, CDKN1A, and PAK3, are related to tumor metastasis and regulation of cell migration." (PMID 28454092, 2017). "The increased expression of CCNE1 might shorten the tumor cell cycle phase, speech up cell proliferation, and be closely involved in LIHC aggressiveness according to the published literatures." (PMID 28316892, 2017). "From the point of view of cancer or tumor research, it was reported that miR-103 is part of the G1/S transition regulatory network, by targeting CCNE1, CDK2, and CREB1 (cAMP responsive element binding protein 1) during IGF-1 simulated proliferation in mouse crypt cells." (PMID 26935418, 2016). "However it is still critical to highlight the findings that in tumor samples with the greatest increase in YAP staining there was a positive correlation with alterations in CCNE1, Cyr61, and CTGF expression." (PMID 27605415, 2016). "Given the well-documented role of cyclin E1 in oncogenesis, it will be of interest to compare cyclin E1-interactomes and cyclin E1-Cdk2 phosphorylation targets in pre-malignant lesions, during tumor initiation, progression, and in the metastatic spread." (PMID 27828963, 2016). "The only clear cell type ovary tumor specimen showed low CCNE1 staining." (PMID 26204491, 2015). "Our preliminary exploration of the mechanisms that LOC401317 utilizes as a tumor suppressor shows that LOC401317 may cause cell cycle arrest by increasing p21 expression and decreasing cyclin D1 and cyclin E1 expression." (PMID 25422887, 2014). "Crizotinib was added to this regimen; however, he had disease progression on this chemotherapy and was referred to our service where tumor sequencing (lung metastases) revealed MET amplification, PI3KCA V344G mutation, CCNE1 amplification, and PTPRD S1845fs*2 mutation." (PMID 25126591, 2014). "CCNE1 gene expression is hypothesized to confer a post-treatment survival advantage to the tumor cells with high-level amplifications conferring a worse prognosis than low-level gains of the CCNE1 region." (PMID 23289505, 2013). "Furthermore, transfection with miR-137mimics suppressed at least two downstream target genes of ERRα–CCNE1 and WNT11, which are important effectors of ERRα implicated in tumor proliferation and migration." (PMID 22723937, 2012). "Uniquely amongst cell cycle proteins in Drosophila, Cyclin E1 over-expression has been shown to promote self-renewal of neuroblasts and may translate to an increased clonogenic capacity in tumor cells." (PMID 21103391, 2010). "Due to the limited availability of antibodies suitable for immunohistochemistry, the expression of cyclin E2 has been examined only through mRNA expression in tumour samples, whereas there is a comprehensive array of literature on the expression of both cyclin E1 protein and mRNA in cancer samples." (PMID 20180967, 2010).
tumor (continued). "CCNE1 is expressed at high levels in multiple tumour types other than breast." (PMID 20180967, 2010). "CCNE1 is an important component in the cell cycle regulation, and as a target in the carcinogenesis, overexpression over cyclin E has been observed in several tumor types." (PMID 17201907, 2007). "Synthetic lethal approaches being investigated in tumor-agnostic studies include PARP inhibitors for BRCA1/2- or ATM-mutant cancers; ATR inhibitors for ATM-mutant cancers; and PKMYT1 inhibition for solid tumors with CCNE1 amplification, FBXW7 loss, and PPP2R1A mutations (NCT04855656)." (PMID 38938274, 2024). "Considering CCNE1 amplification causes replication stress that activates the DNA replication fork stabilizer and regulator of G2/M checkpoint kinase ATR, we sought to further improve anti-tumor efficacy by combining PKMYT1 inhibition (RP-6306) with ATR inhibition (RP-3500)." (PMID 38410486, 2024). "In addition to promoting genomic instability, CCNE1 amplification may also modulate the tumor-immune microenvironment." (PMID 38717153, 2024). "Preclinical studies suggest that although proliferation of these tumors is primarily CDK4/6-dependent, resistance to CDK4/6i monotherapy might be driven by CDK2 activity, and clinical data has shown a correlation between high tumor CCNE1 mRNA levels and impaired response to combined CDK4/6i +/- ET." (PMID 38047585, 2024). "Consequently, combined CDK2 and AKT inhibition may have synergistic anti-tumor activity against CCNE1-amplified tumors and hold promise for clinical development." (PMID 38894867, 2024). "Notably, this correlation suggests CCNE1’s involvement in modulating the tumor microenvironment, which could influence immune cell recruitment and activation, thus presenting potential therapeutic implications for enhancing cancer immunotherapy effectiveness." (PMID 39591374, 2024). "However, CCNE1 expression was negatively correlated with tumor grade in CHOL, OV and READ." (PMID 36964635, 2023). "Therefore, we analyzed the correlation between tumor mutation burden and the expression of targets, and the results showed that the expression of AURKA, CCNA2, CCNE1, CDK1, CHEK1, and PLK1 were significantly positively correlated with the tumor mutation burden." (PMID 36483630, 2022). "Therefore, high expression of CDCA5 could play a significant role in tumor progression, invasion, and metastasis via cyclin E1." (PMID 36428736, 2022). "Here, we quantified whether the cancer cell specific gene expression levels and variability of CCNE1 and DDIT3, a proapoptotic transcription factor found to be part of the stress-associated tumor cell population enriched after chemotherapy in HGSC26, are associated with patient outcomes." (PMID 35169222, 2022). "Therefore, Bcl-2 and CCNE1 might contribute to the tumor promoting role of the NUDT21/SGPP2 pathway." (PMID 34660260, 2021). "For example, CCNE1 (Cyclin E1) is an established oncogene that is genomically amplified in many cancer types and whose overexpression induces CIN, which is associated with cell cycle misregulation, genome instability, cellular transformation and tumor formation in mice." (PMID 35008511, 2021). "CCNE1 amplification has also been observed in some other tumors and may lead to continuously activated DNA and centrosome replications, inducing chromosomal instability and tumor growth." (PMID 33194720, 2020). "Analysis of ctDNA or tumor mRNA from patients enrolled in the PALOMA-3, NeoPalAna and MONALEESA-3 trials have identified Rb mutations, activating mutations in PIK3CA and ESR1, increased cyclin E1 and activation of the PDK1-AKT axis as some of the drivers of resistance." (PMID 32344635, 2020).
tumor (continued). "The result showed that tumor tissues had a significantly higher mRNA expression than adjacent tissues (P<0.0001) and the up-regulation expression of CCNE1 relative to the GC tissue was found in 35 cases, what was more, protein expression of CCNE1 had similar results with RNA (P<0.01)." (PMID 31072916, 2019). "Analysis of tumor lysates from control and metformin-treated mice showed an obvious increase in expression of phosphorylated AMPKa proteins; and there was a significant decrease in Yap1, CCNE1 and CCNE2 protein levels in tumors from mice treated with metformin." (PMID 31455378, 2019). "Furthermore, the latest study showed that the overexpression of CCNE1 in HER2 positive tumor can impair the anti-HER2 therapy through resulting in resistance to trastuzumab both in vitro and in vivo, whereas the mechanisms leading to CCNE1 over-expression in these cells are unclear." (PMID 22723937, 2012). "Although we were unable to generate stable OVCAR-3 with integrated shRNA directed to CCNE1 to further validate these findings in vivo, these observations suggest that CCNE1 amplification may enhance the ability of tumor cells to repopulate the tumor after the cessation of chemotherapy." (PMID 21103391, 2010). "Data from cancer studies have already identified that cyclin E1 and E2 are frequently not co-expressed in tumours, and may have distinct associations with recurrent disease." (PMID 20180967, 2010). "However, cyclin E2 modulation does not always lead to changes in cyclin E1 expression, for example in smooth muscle cells the cyclin E2 siRNA treatment leads to downregulation of cyclin E1, and cyclin E1 and E2 are co-expressed in other tissues, and in some tumours." (PMID 20180967, 2010). "Our data demonstrated that CCNE1 knockdown inhibited the progression of TNBC by restraining proliferation, migration and tumor growth as well as enhancing apoptosis." (PMID 40346052, 2025). "LMW-cyclin E1 has been shown to bind more efficiently to CDK2 and to mediate multiple biological processes in tumor progression, such as drug resistance and tumor metastasis." (PMID 40959067, 2025). "Among them, seven cancer genes (ERBB2, ERBB3, PPARG, MYC, CCND1, CCNE1, MDM2) were detected to be amplified in both ctDNA and tumor tissues, indicating the reliability of ctDNA in reflecting the genomic features of tumors." (PMID 40191434, 2025). "The multivariate analysis included tumour stage and CDK4, CDK6, CDK2, cyclin D1, cyclin E1, RB1 and pRB1 protein expression." (PMID 38612869, 2024). "Immunofluorescence staining confirmed flow cytometry results and showed a net enrichment of glyCAF at the tumor margin, near CD8+ T cells in the Ccne1+ model." (PMID 38509063, 2024). "PPP2R2B is a regulatory subunit of a PP2A heterotrimeric complex, which has a role in recognizing dephosphorylated substrates, including cyclin E1 and PDK1, which participate in the cell cycle and tumor proliferation." (PMID 38976080, 2024). "In the orthotopic mouse metastasis model, Ccne1, or cyclin E1, was upregulated, and pharmacological inhibition of CDK2 repressed tumor growth and metastasis." (PMID 38916046, 2024). "The retinoblastoma 1 (Rb1) gene is deleted in 8% and mutated in 2% of HGSOCs, while amplification of the cyclin E1 gene, CCNE1, one of the most common focal copy number change events in HGSOC, occurs in 20% of tumours." (PMID 38785992, 2024). "One triple-proficient patient with an intermediate TMB had amplifications of CCNE1 and ERBB2 in all tumor samples (>20 additional copies), supporting oncogene amplification as a driving mechanism in the absence of DNA damage repair deficiency." (PMID 38175731, 2024). "A comparison of differentially expressed genes was then carried out for CCNE1 and CDK2, where a subset of genes was identified to be altered in the high-expression tumours." (PMID 38612869, 2024).